ADAMTS14 (ADAM metallopeptidase with thrombospondin type 1 motif 14)
Diseases named in the same sentence as ADAMTS14 in open-access papers:
ADAMTS14 is named in the same sentence as 35 diseases in open-access papers, as found by Europe PMC text mining. Sharing a sentence is not in itself a finding about the gene and the disease. The quoted sentences say what the papers report.
hepatocellular carcinoma (5 papers, 2017 to 2025). A malignant tumor that arises from hepatocytes. "However, whether ADAMTS14 genetic variants play a role in hepatocellular carcinoma (HCC) susceptibility remains unknown." (PMID 28231306, 2017). "At the same time, ADAMTS14 is significantly upregulated in breast cancer and can lead to the progression of oral and liver cell carcinomas." (PMID 40224547, 2025).
oral cancer (4 papers, 2016 to 2022). "ADAMTS14 gene polymorphisms as a risk factor for oral cancer together with environmental carcinogens (betel nut chewing and smoking) contribute to oral cancer initiation." (PMID 33345447, 2021). "In the present study, we for the first time revealed that the combination of the ADAMTS14 gene polymorphisms with the behavioral use of betel nut and tobacco conferred a higher susceptibility to oral cancer." (PMID 27463966, 2016). "In conclusion, our results demonstrate that a joint effect of ADAMTS14 SNPs (rs10823607, rs12774070, rs4747096, and rs61573157) with betel nut chewing and smoking causally contributes to the occurrence of oral cancer." (PMID 27463966, 2016). "In the present study, we showed a significant interaction between betel nut chewing and the presence of at least one polymorphic allele of four ADAMTS14 SNPs examined is associated with higher incidence of oral cancer in smokers." (PMID 27463966, 2016). "In this study, 850 patients with oral cancer and 1200 normal controls were recruited to explore the risk effect of ADAMTS14 gene polymorphisms (rs10823607, rs12774070, rs4747096, and rs61573157) on the development of oral neoplasm." (PMID 27463966, 2016). "Four single-nucleotide polymorphisms (SNPs) of the ADAMTS14 gene, including rs10823607, rs12774070, rs4747096, and rs61573157 were evaluated from 1200 normal controls and 850 patients with oral cancer." (PMID 27463966, 2016). "Associations of combined effects of ADAMTS14 genotypic frequencies and betel nut chewing with oral cancer among 1401 smokers." (PMID 27463966, 2016). "Associations of genotype frequencies of ADAMTS14 rs12774070 with clinical status of oral cancer among 694 betel quid users." (PMID 27463966, 2016). "The single nucleotide polymorphism of ADAMTS14 is closely related to liver cancer and oral cancer." (PMID 32884571, 2020). "Though the genetic contribution alone appears to be subtle, a significant interaction between betel nut chewing and the existence of at least one polymorphic allele of these four ADAMTS14 SNPs is shown to be correlated with the incidence of oral cancer in smokers." (PMID 27463966, 2016). "There data suggest that changes in ADAMTS14 expression and function due to genetic polymorphisms, in combination with betel quid chewing, may affect tumor cell differentiation of oral cancer." (PMID 27463966, 2016). "However, while considering behavioral exposure of environmental carcinogens, the presence of four ADAMTS14 SNPs, combined with betel nut chewing and/or smoking, profoundly leveraged the risk of oral cancer." (PMID 27463966, 2016). "However, little is known regarding the joint effects of ADAMTS14 gene polymorphisms and behavioral exposure of cancer-causing substances on the predisposition to oral cancer." (PMID 27463966, 2016). "Distributions of genotypic frequencies of ADAMTS14 SNPs in controls and oral cancer patients." (PMID 27463966, 2016). "We failed to individually detect any significant association of these ADAMTS14 variants with the occurrence of oral cancer between two study groups either with or without the adjustment for betel quid chewing, cigarette smoking, and alcohol drinking." (PMID 27463966, 2016). "Furthermore, the functional role of ADAMTS14 in cell differentiation of oral cancer requires further investigation." (PMID 27463966, 2016).
osteoarthritis (4 papers, 2022 to 2023). A noninflammatory degenerative joint disease occurring chiefly in older persons, characterized by degeneration of the articular cartilage, hypertrophy of bone at the margins and changes in the synovial membrane. "Current evidence of the association between a single nucleotide polymorphism (SNP) in ADAMTS14 (rs4747096) and osteoarthritis (OA) is controversial." (PMID 37550675, 2023). "shed light on the significant correlations between ADAMTS14 rs4747096 polymorphism and the osteoarthritis of the temporomandibular joint in Chinese Han women." (PMID 35572505, 2022). "Significant upregulation of ADAMTS14 was observed in human osteoarthritis (OA) cartilage, suggesting its involvement in cartilage matrix anabolism." (PMID 35347083, 2022).
breast carcinoma (3 papers, 2022 to 2025). "Porter has reported that ADAMTS14 expression was noticeably elevated in human breast cancer." (PMID 36186476, 2022).
liver cancer (3 papers, 2017 to 2020). An epithelial or non-epithelial malignant neoplasm that arises from the liver. "In addition, the liver-cancer associated risk [T]-allele creates the average HM vector of the ADAMTS14 PRR domain compared to the [C]-allele, which results in a decreased length of HM vector [HM vector change: 4.5%, from 4.696 (kTÅ/e) to 4.906 (kTÅ/e)]." (PMID 28231306, 2017).
oral squamous cell carcinoma (3 papers, 2020 to 2022). "Low cytoplasmic expression of ADAMTS14 has been associated with poor overall survival of patients with oral squamous cell carcinoma, which may be used as a novel biomarker for oral squamous cell carcinoma diagnosis." (PMID 33932142, 2021). "However, whether the expression of ADAMTS14 is correlated with the carcinogenesis and progression of oral squamous cell carcinoma (OSCC) has not yet been investigated." (PMID 32102222, 2020).
colorectal cancer (2 papers, 2019 to 2022). A primary or metastatic malignant neoplasm that affects the colon or rectum. "presented that disrupting the ADAMTS14 methylation patterns might lead to predictive biomarkers for colorectal cancer." (PMID 35572505, 2022).
melanoma (2 papers, 2020 to 2022). A malignant, usually aggressive tumor composed of atypical, neoplastic melanocytes. "With respect to the relationship between the level of baseline sPD-L1 and transcripts encoding 60 metalloproteases, ADAM11, ADAM20 and ADAMTS14 were identified as associated with higher baseline sPD-L1 levels in both CheckMate 009/RCC and CheckMate 038-P1/melanoma (t-values >1.5)." (PMID 35131863, 2022). "Indeed, it resulted quite appealing the fact that such positive association did occur with high expression of other ADAMTS proteases (ADAMTS2, ADAMTS4, ADAMTS5, ADAMTS9, ADAMTS12 and ADAMTS14) that definitively implied a key role of these proteases during melanoma progression." (PMID 32230715, 2020).
pulmonary fibrosis (2 papers, 2023 to 2025). Chronic progressive interstitial lung disorder characterized by the replacement of the lung tissue by connective tissue, leading to progressive dyspnea, respiratory failure, or right heart failure. "But so far, no studies have been able to clarify ADAMTS14's role in pulmonary fibrosis." (PMID 36681777, 2023). "Like HS6ST2, ADAMTS14 is also mainly present in extracellular matrix, which may suggest that the composition or structure of extracellular matrix is also an important pathological factor that should not be ignored in pulmonary fibrosis." (PMID 36681777, 2023).
renal carcinoma (2 papers, 2019 to 2022). A carcinoma arising from the epithelium of the renal parenchyma or the renal pelvis. "In addition, we examined the expression patterns of ADAMTS14 in various cancer cell lines in the CCLE database containing renal cancer." (PMID 35572505, 2022).
Alzheimer disease (1 paper, 2022). A progressive, neurodegenerative disease characterized by loss of function and death of nerve cells in several areas of the brain leading to loss of cognitive function such as memory and language. "ADAMTS14 was also linked to the susceptibility to aging-related Alzheimer's disease as well as the regulation of immune functions via TGF-beta signaling." (PMID 35347083, 2022).
atopic dermatitis (1 paper, 2021). "Finally, the peculiar atopic dermatitis-like skin phenotype of mice deficient in both ADAMTS2 and ADAMTS14 also points to yet to be discovered new substrates of these two related enzymes." (PMID 33816558, 2021).
glioblastoma (1 paper, 2020). The most malignant astrocytic tumor (WHO grade IV). "Among genes whose high expression correlates with decreased survival in glioblastoma, we identified several components of the “matrisome” and associated factors (FAM20C, SEMA3F, ADAMTSL4, ADAMTS14, SERPINA5, and CRELD1)." (PMID 32488114, 2020).
keratoconus (1 paper, 2020). A degenerative, structural disorder of the eye, characterized by a cone-shaped protrusion of the cornea. "In addition, a combination of genes significantly upregulated in the KJ samples only, S100A8, S100A9, ADAMTS14, LYPD2 and AOC1 may yield distinguishing biomarkers for subtypes of keratoconus." (PMID 32555404, 2020).
lymph node metastasis (1 paper, 2020). "Univariate and multivariate analyses confirmed that cytoplasmic expression of ADAMTS14 was associated with lymph node metastasis, tumor stage, and tumor grade and also indicated that cytoplasmic ADAMTS14 expression may be an independent prognostic factor for OSCC." (PMID 32102222, 2020). "Our findings revealed that negative cytoplasmic expression of ADAMTS14 was significantly associated with lymph node metastasis and AJCC cancer stage." (PMID 32102222, 2020). "Moreover, univariate analysis revealed that negative ADAMTS14 expression was associated with worse survival, lymph node metastasis, more advanced tumor stages, and higher histological grades in OSCC patients." (PMID 32102222, 2020). "In analyzing correlations between ADAMTS14 expression and clinicopathological features, we found that negative cytoplasmic expression of ADAMTS14 was significantly associated with higher frequencies of lymph node metastasis and more advanced AJCC stages (III/IV)." (PMID 32102222, 2020). "Negative cytoplasmic expression of ADAMTS14 was significantly correlated with lymph node metastasis (p = 0.003) and AJCC cancer stage (p = 0.031) using Fisher’s Exact Test or Chi-square test." (PMID 32102222, 2020).
lymphedema (1 paper, 2022). Excess fluid collection in tissues, causing swelling. "The absence of ADAMTS2 or ADAMTS14 does not involve massive edema in our mouse models, suggesting that mutations in these genes should not be responsible for primary lymphedema." (PMID 35316211, 2022).
renal cell carcinoma (1 paper, 2022). "By means of GSEA, we identified five ADAMTS14-related signaling pathways, including MTOR, PPAR, INSULIN signaling pathway, renal cell carcinoma, and renin–angiotensin system." (PMID 35572505, 2022). "According to the threshold of the |NES| >1.5 and nominal p-value < 0.05, we identified five signaling pathways that showed significantly different enrichment in the ADAMTS14 expression phenotype, including INSULIN, MTOR, PPAR, renal cell carcinoma, and renin–angiotensin system pathways." (PMID 35572505, 2022).
tumor (12 papers, 2015 to 2025). "For the associations between ADAMTS14 and immunity, our results found that the ADAMTS14 expression was markedly linked to tumor immune microenvironment, immune cells, and immune checkpoint molecules." (PMID 35572505, 2022). "In this study, our results indicated that ADAMTS14 displayed a higher expression in ccRCC tumor tissues than in adjacent normal tissue specimens, associated with poor OS." (PMID 35572505, 2022). "Moreover, ADAMTS14 belongs to the family of metalloproteases (ADAMTSs), which represent complex extracellular proteases that have been associated to both oncogenic and tumor-protective contexts." (PMID 33572758, 2021). "In addition, the genetic association of non-synonymous single nucleotide polymorphisms (nsSNPs) in ADAMTS14 proteases to influence osteoarthritis phenotypes and tumour microenvironment has been reported." (PMID 28231306, 2017). "Consistent with the mRNA expression levels of ADAMTS14, its protein expression levels were also elevated in ccRCC tumor tissues." (PMID 35572505, 2022). "ADAMTS14 displayed a higher expression in ccRCC tumor tissues than in adjacent normal tissues (p-value <0.001)." (PMID 35572505, 2022). "ADAMTS14 displayed a higher expression in ccRCC tumor than in adjacent normal tissues, and further validated results of the ICGC dataset; qRT-PCR and immunohistochemistry remained consistent (all p < 0.05)." (PMID 35572505, 2022). "As for the tumor microenvironment, significant results were also shown between ADAMTS14 and ESTIMATE, Stromal, and Immune scores." (PMID 35572505, 2022). "This is the first study to report that the cytoplasmic expression level of ADAMTS14 is associated with OSCC prognosis and tumor progression." (PMID 32102222, 2020). "ADAMTS14 protein, a metallopeptidase that degrades the extracellular matrix and its components, and thus increases cell migration and invasion, was found to be expressed in the tumor cells." (PMID 38473790, 2024). "Additionally, voltage-gated ion channels and genes like KCNQ5, KCNV1, ADAMTS14, MPPED1, and SLC24A2 are linked to tumor traits in these tumors." (PMID 39139281, 2024). "Moreover, the expression of ADAMTS14 was remarkably associated with immune checkpoint molecules, tumor mutational burden (TMB), immune cells, and tumor immune microenvironment (all p < 0.05)." (PMID 35572505, 2022). "ADAMTS14 proteins were found to be expressed in the cytoplasm of tumor cells." (PMID 32102222, 2020). "Moreover, we observed a significant association of rs12774070, which is predicted to alter the expression and function of ADAMTS14 by in silico and bioinformatics analyses, with poor tumor cell differentiation (AOR: 0.59; 95% CI: 0.38–0.92; p = 0.02) in patients who chewed betel nuts." (PMID 27463966, 2016). "We explored the relationship between ADAMTS14 and MGMT methylation in normal and tumor tissues of CRC patients and correlated these findings with tumor genotype and phenotype, including clinico-histological parameters." (PMID 25638164, 2015). "Moreover, we shed light on the fact that the expression of ADAMTS14 was remarkably related to immune cells, TMB, immune checkpoint molecules, and tumor immune microenvironment." (PMID 35572505, 2022). "In the absence of ADAMTS14, fibulin 2 levels are increased, and fibulin 2 in turn outcompetes latent TGFβ for binding to Fibrillin, facilitating the release of active TGFβ into the tumour milieu." (PMID 37929635, 2024). "Moreover, we analyzed the correlation among four-gene signature (FeSig) (BID, TAZ, MT1G, and SLC7A11), downstream hub genes (CPNE7, WNT10B, ADAMTS14, and RUFY4), and immune checkpoints (PD-1, CTLA4, LAG3, and TIGIT) to further discover potential molecular mechanisms of tumor immunity." (PMID 34367965, 2021).
cancer (9 papers, 2016 to 2023). A tumor composed of atypical neoplastic, often pleomorphic cells that invade other tissues. "More intriguingly, we identified an inverse association of ADAMTS14 rs12774070 with cancer cell differentiation in the present study." (PMID 27463966, 2016). "In HCC, ADAMTS14 expression has been associated with more aggressive cancers and poorer clinical outcomes, which are rs12774070 variants in the TSR domain near the glycosylation site, which may affect the TSR domain and alter cell surface association and sequential processing mechanisms." (PMID 32102222, 2020). "As for pan-cancer immune subtypes, our results indicated that ADAMTS14 was differently expressed in pan-cancer immune subtypes of C1, C2, C3, C4, and C6 (p-value = 0.001)." (PMID 35572505, 2022). "ADAMTS14 played a crucial role in the formation and development of various cancers." (PMID 35572505, 2022). "They play a dual role in cancer; for instance, ADAMTS14 works as a promoter of hypermethylation and acts as a tumor suppressor gene, whereas others show upregulation in cancer acting as oncogenes, including ADAMTS12, which regulated the cell proliferation and migration in colorectal cancer." (PMID 35743687, 2022). "However, GSEA identified several cancer-related signaling pathways including INSULIN, MTOR, and PPAR pathways that were enriched in the low-ADAMTS14 expression group." (PMID 35572505, 2022). "ADAMTS14 belongs to the ADAMTS protein family, which are secreted zinc metalloproteases that play a role in the extracellular matrix related to angiogenesis and cancer." (PMID 33946379, 2021). "However, the downregulation of ADAMTS2, ADAMTS14, MMP11, and MMP7, metalloproteases that help in cancer cell invasiveness by dissolving the ECM components, could prevent cancer invasive potential." (PMID 37834191, 2023). "In addition, the correlations between negative ADAMTS14 protein expression and lymph node metastasis and between ADAMTS14 and AJCC cancer stage indicate that ADAMTS14 could be involved in OSCC metastasis." (PMID 32102222, 2020).
ADAMTS14 also shares sentences with these, for which no sentence is quoted: knee osteoarthritis (3 papers); clear cell renal cell carcinoma (2); tendinopathies (2); cardiovascular disease (1); cervical cancer (1); diabetes (1); endometrial cancer (1); glioma (1); head and neck squamous cell carcinoma (1); lung carcinoma (1); lymphoma (1); neuroblastoma (1); ovarian carcinoma (1); pancreatic cancer (1); stomach cancer (1); thyroid cancer (1).